INS (insulin)
Diseases named in the same sentence as INS in open-access papers (continued):
Sharing a sentence is not in itself a finding about the gene and the disease.
diabetes (continued). "Analysis of diabetes medications stratified by HbA1c at the time of HTX showed a significantly higher percentage of regular insulin (P = 0.009) and insulin glargine (P = 0.028) in T2DM patients with a HbA1c ≥ 7.0%." (PMID 35757347, 2022). "Previous studies have shown that the prevalence of diabetes in the elderly is high, but at present, many studies show significantly lower insulin sensitivity in obese young adults." (PMID 35811955, 2022). "Specific deletion of islet β cell cilia not only impairs insulin secretion, but also affects glucagon and somatostatin secretion of proximal α and δ cells, leading to diabetes." (PMID 36552853, 2022). "Diabetes mellitus is a long-lasting endocrine ailment triggered by abnormalities in the production of insulin by pancreatic cells and its actions in outlying tissues, resulting in metabolic abnormalities." (PMID 35335923, 2022). "Insulin-level analysis should also contribute to verification of cinnamon’s impact on diabetes, suggesting its inclusion in further studies." (PMID 35458138, 2022). "To compare the efficacy and safety of metformin, glyburide, and insulin for GDM, we conducted a subgroup analysis of outcomes for women with GDM according to the International Association of Diabetes and Pregnancy Study Groups (IADPSG) diagnostic criteria." (PMID 36530712, 2022). "This gene is therefore relevant to diabetes, since zinc is an essential co-factor for insulin metabolism in the pancreatic β-cell." (PMID 35884374, 2022). "The aim was to describe experiences of the reconciliation process when living with insulin treated diabetes." (PMID 35726172, 2022). "The aim of the study was to describe experiences of the reconciliation process living with insulin treated diabetes." (PMID 35726172, 2022). "The glibenclamide treatment of diabetes in a transgenic mice model of HD showed beneficial effects, suggesting a stimulatory action on insulin exocytosis." (PMID 35615716, 2022). "Elevated levels of mitochondrial iron and reactive oxygen species (ROS) accompany the progression of diabetes, negatively impacting insulin production and secretion from pancreatic cells." (PMID 35538231, 2022). "Using a Cox-regression model, a comparison between groups was made after adjustment for factors shown to correlate with mortality (age, diabetes severity score and insulin use), with HR = 0.68 (95% CI: 0.38–1.19, p = 0.18) in favour of the intervention." (PMID 35089082, 2022). "Diabetes physiology in the ESKD patient is different and more complex than in the general diabetes population, with significant alterations of both glucose and insulin homeostasis." (PMID 36992784, 2022). "This consequently dampens insulin signaling and therefore targeting this interaction puts forth potential therapeutic strategies to normalize aberrant insulin signaling and metabolism within the skeletal muscle as is observed in obesity and diabetes." (PMID 35842608, 2022). "Most of the treatments for this type of diabetes manage to increase insulin secretion by pancreatic β-cells, reducing blood glucose and glycosylated hemoglobin levels." (PMID 36233271, 2022). "The study by Luo used the INS-1 cells, which are a widely used and well-established model for the study of diabetes and their property of glucose-stimulated insulin secretion." (PMID 36231063, 2022). "The majority of patients with diabetes in Singapore have type 2 diabetes, which is influenced by modifiable lifestyle factors and characterised by insulin resistance along with diminished insulin secretion." (PMID 35172774, 2022). "High-fiber diets not only improve diabetes control, but also reduce insulin requirements and the incidence of complications." (PMID 36231475, 2022). "Diabetes mellitus is a carbohydrate metabolism disorder produced mainly by a deficit in insulin production or insulin resistance." (PMID 35993079, 2022).
diabetes (continued). "Among the factors significantly predicting the high-risk groups of adolescent diabetes were higher BMI, FPG, HbA1c, and insulin in both sexes." (PMID 36010139, 2022). "Downregulation of HDACs has been shown to assist in skeletal muscle insulin sensitivity and pharmacological inhibition of HDACs has been postulated as a viable therapeutic intervention for diabetes." (PMID 35842608, 2022). "Data sources: We performed a narrative review, based on relevant articles written in English from a Pubmed search, using the following search terms: “resveratrol”, “obesity”, “Diabetes Mellitus”, and “insulin sensitivity”." (PMID 35889827, 2022). "Diabetes mellitus (DM) is a metabolic disease that promotes plasma hyperglycemia, secondary to reduced insulin secretion and/or resistance to its peripheral action." (PMID 35620400, 2022). "Diabetes mellitus (DM) is a chronic metabolic disorder characterized by persistent hyperglycemia due to insulin resistance or failure to produce insulin." (PMID 36247456, 2022). "In the Diabetes Outcomes in Veterans Study, 204 patients with type 2 diabetes receiving insulin treatment were included and underwent 8-week self-monitoring of blood glucose levels." (PMID 36463197, 2022). "A wide array of insulin types are available for the chronic management of diabetes mellitus in dogs, which vary in potency, speed of absorption and duration of action." (PMID 35152907, 2022). "It was proposed that the influence of COVID-19 infection was amplified by DPP4 in patients with diabetes, and through its interaction with INS, leptin, IL-6 and other proteins." (PMID 34996987, 2022). "In diabetes, local and systemic acidosis reduces insulin’s affinity for its receptor, exacerbating the spiral of peripheral insulin resistance." (PMID 36297518, 2022). "In this study, the realization of continuous real-time detection of glucose and insulin in saliva demonstrated its possibility of becoming a precise and real-time monitoring tool for diabetes management." (PMID 35957227, 2022). "Diabetes mellitus is a chronic metabolic disorder characterized by persistent hyperglycemia resulting from insufficiency in insulin action or insulin secretion, or both." (PMID 36296407, 2022). "The duality of these enzymes and receptors’ effects on the insulin signaling pathway makes S1P’s role in diabetes controversial." (PMID 36499769, 2022). "In an elastase-induced emphysema Wistar rat model with alloxan-induced diabetes, diabetic rats had significantly lower leukocyte infiltration into the lungs, which was significantly increased upon subcutaneous treatment with insulin." (PMID 35273609, 2022). "Nowadays, limited treatments are palliative and largely based on disease symptoms, for example, insulin or hypoglycemic drugs for patients with diabetes, and cardiac electronic implantable devices for patients with heart block." (PMID 35972936, 2022). "Type 2 diabetes mellitus (T2D) is a major public health concern and is characterized by sustained hyperglycemia due to insulin resistance and destruction of insulin‐producing β cells." (PMID 36257905, 2022). "GPR40, a G protein-coupled receptor for free fatty acids (FFAs), is considered as a therapeutic target for type 2 diabetes mellitus (T2DM) since GPR40 activation in pancreatic beta cells enhances glucose-stimulated insulin secretion." (PMID 36331958, 2022). "Diabetes is a lifelong disease characterized by hyperglycemia distinguished by insufficient insulin secretion and/or dysfunction, resulting in metabolic disorders such as carbohydrates, fats, and proteins." (PMID 35399638, 2022). "The study was a post-hoc analysis of AIM (the effect of Acarbose on glycemic variability in patients with type 2 diabetes mellitus using premixed Insulin compared to Metformin) study." (PMID 36273168, 2022).
diabetes (continued). "ACC2 KO mice with HF diet show reduced AKT level and increased phosphorylation of AKT, which is critical in the insulin signaling pathway that can protect the mice from diabetes." (PMID 35359351, 2022). "Limitations of the study apply to the relatively small number of patients who displayed a well-controlled non-insulin requiring diabetes and were characterized in considerable detail." (PMID 35662921, 2022). "The results demonstrate that birth weight is the strongest predictor of cord blood leptin, with maternal BMI and diabetes having a greater influence on insulin than leptin." (PMID 35197933, 2022). "Nevertheless, the used insulin treatment normalized, either fully or partly, expression of the other diabetes-modified genes studied, indicating that the regulation of Cyp2r1 is rather unusual." (PMID 35524739, 2022). "Stem cells are a renewable source of pluripotent cells, which can be utilized to insulin-producing β cells repair and regeneration during diabetes treatment." (PMID 35395037, 2022). "In 1923, insulin became the first commercial peptide drug and has since benefited thousands of diabetes patients to date." (PMID 35165272, 2022). "In the last three decades many insulin analogues have been generated to provide effective options for the treatment of diabetes." (PMID 35832429, 2022). "Environmental chemical exposure was also utilized to predict 2-h plasma glucose after OGTT (2-h PG after OGTT), blood insulin, diabetes mellitus, and FPG by LASSO regression and RF." (PMID 36572938, 2022). "Proteinuria, basal insulin dose, diabetes duration, and HbA1c turned out to be the most important clinical predictors of NH at 15 min and 30 min PHs." (PMID 36013211, 2022). "The prevalence of diabetes, acromegaly, and pancreatic inflammation were predicted using insulin activity and the ratio of pancreatic lipase concentration to creatinine." (PMID 36230305, 2022). "In diabetes mellitus, reduced HSP expression is associated with the decreased ability of insulin-sensitive tissues to respond to stress." (PMID 35101146, 2022). "From the 30 largest clusters, 6 refer to nutrition, 4 to diabetes, and 3 to each of insulin, emotions, and the health care system." (PMID 35852829, 2022). "The two common types of diabetes (insulin-dependent (type 1) and non-insulin-dependent (type 2)) occur when the body cannot properly store and use glucose." (PMID 35631811, 2022). "Diabetes mellitus is a metabolic disorder characterized by the failure of insulin secretion by pancreatic β-cells, or poor responses of cells to insulin." (PMID 35164311, 2022). "One of the human cohorts had a higher range of fasting insulin because the study included diabetic living with diabetes and severe insulin resistance needing insulin injection (T2D‐SI group)." (PMID 34921686, 2022). "A study compared neuropsychological features between adults with permanent neonatal diabetes mellitus (PNDM) caused by KCNJ11 variations and by INS variations (the gene encodes insulin; its variations influence insulin synthesis)." (PMID 35654594, 2022). "In the analysis related to all diabetes ICSRs, dapagliflozin was associated with a 12.7- and 7.6-fold increased reporting frequency of ketoacidosis adverse events compared to DPP-4is and insulin, respectively." (PMID 35337085, 2022). "The first injection of insulin on January 11, 1922, to a 14-year-old boy with the use of reusable glass-bodied syringes started an entirely new era of diabetes management and led to the improvement of insulin delivery methods." (PMID 35355552, 2022). "Diabetes often co-occurs with depression and anxiety, suggesting that insulin malfunctioning can play a role in mental changes." (PMID 36232867, 2022). "Randomized control trials have shown that frequent flash glucose monitoring can reduce time spent in hypoglycemia for type 1 diabetes patients with well-controlled diabetes, as well as in type 2 diabetes patients on intensive insulin therapy." (PMID 35501880, 2022).
diabetes (continued). "The pathophysiological factors in patients with diabetes that drive the development of cardiomyopathy include oxidative stress, insulin resistance, inflammation, autophagy, cell apoptosis, and pyroptosis." (PMID 36091756, 2022). "Type 1 diabetes mellitus (T1D) is a chronic disease characterized by an autoimmune destruction of insulin-producing β-pancreatic cells." (PMID 35840987, 2022). "Although experiments in vitro and in mouse models of diabetes suggest a potential role of GM3 in competing with the insulin–insulin receptor interaction and to contribute to T2D, robust evidence using GM3 synthase specific inhibitors is needed." (PMID 36499769, 2022). "Basal insulin dose, diabetes duration, proteinuria, and HbA1c were the most important clinical predictors of NH assessed by RF." (PMID 36013211, 2022). "Long-term intake of high-energy diet can lead to decreased insulin sensitivity and even insulin resistance, eventually leading to diabetes." (PMID 35811955, 2022). "One major focus of studies with natural products for diabetes treatment (particularly through molecular docking) is on those ligands that offer effectors for proteins involved in insulin signaling." (PMID 35356248, 2022). "Most people with IGT and higher insulin response in the present study have deterioration of diabetes during the 30-year follow-up period." (PMID 35090539, 2022). "While Pb is known to trigger oxidative stress by activating reactive oxygen species (ROS), and inhibiting the insulin-signaling pathway, several studies have found that it increased insulin resistance and diabetes." (PMID 36232070, 2022). "Declines in either plasma insulin or the sensitivity to insulin in diabetes would be expected to lift its inhibition of cAMP‐mediated responses to glucagon." (PMID 35569125, 2022). "Here, mixed multiple layer-by-layer (mmLbL)-INS microspheres were developed for glucose-mediated INS release and an enhanced hypoglycemic effect for diabetes care." (PMID 36246353, 2022). "Diabetes mellitus (DM) is a metabolic syndrome with abnormality in the metabolism of carbohydrates, protein and lipids, and which is characterized by an absolute and relative deficiency of insulin secretion." (PMID 36363561, 2022). "For dexamethasone-treated or diabetic rabbits, DHEA improved insulin sensitivity, lipid levels, directly inhibited renal gluconeogenesis, delayed the onset of diabetes, and alleviated renal oxidative stress and albuminuria." (PMID 35784547, 2022). "The FM and endocrinologist cohorts were also matched (23,407 vs. 23,407) Patients under the care of endocrinologists had a significant 0.5 times more insulin prescriptions per month and almost spent twice as much on diabetes care." (PMID 35330461, 2022). "The main results showed that the participants diagnosed with T2DM had poor diabetes knowledge for total knowledge (96.7%), general knowledge (71.7%), and insulin use knowledge (92.3%)." (PMID 36527016, 2022). "Type 1 diabetes mellitus (T1DM) is characterized by an insufficient insulin level, while type 2 diabetes mellitus (T2DM) is accompanied by insulin resistance (IR) and dysregulation of glucose utilization." (PMID 35844917, 2022). "Diabetes mellitus (DM) is a global public health concern characterized by elevated plasma glucose (hyperglycemia) due to failures in insulin production, action, or a mixture of both." (PMID 35455929, 2022). "Cell therapy to replace β-cells is a potential therapeutic avenue to treat diabetes, but the production of insulin-secreting replacement cells requires reliable tools to assess islet cellular identity." (PMID 35440614, 2022). "Multiple of the top DMPs were annotated to genes with relevant functions for diabetes including SREBF1, associated with obesity, type 2 diabetes and insulin sensitivity; ABCG1, involved in cholesterol and phospholipids transport; and HDAC1, of the HDAC family." (PMID 36529747, 2022).
diabetes (continued). "Digital and wireless technologies are widely available to support lifestyle and treatment interventions as well as diabetes medical devices, such as blood glucose meters, continuous glucose monitoring devices, and smart insulin pens and pumps." (PMID 35900826, 2022). "Typically, patients secrete insufficient insulin (i.e., type 1 diabetes mellitus–T1DM) or develop insulin resistance (i.e., type 2 diabetes mellitus–T2DM), which leads to elevated blood glucose levels (hyperglycemia)." (PMID 36015183, 2022). "Of note, especially insulin secretion and glucose uptake into muscle and adipose tissue are impaired in early insulin resistance as well as in manifest type 2 diabetes mellitus." (PMID 35426970, 2022). "A similar study in specific-pathogen-free C57BL/6 mice with alloxan induced diabetes found that insulin treatment of alveolar macrophages decreased LPS-induced TNF-α and IL-6 production ex vivo." (PMID 35273609, 2022). "In the diabetes group, there was an 80% decrease in the insulin positive cell number compared to the control group (P < 0.001), neither GQD nor metformin treatment increased insulin cell expression compared to the diabetes group." (PMID 35858880, 2022). "As a concluding remark, insulin sensitivity and resistance can actas surrogate marker in managing diabetes thereby preventing its complications." (PMID 37432671, 2022). "Diabetes is a metabolic disorder characterized by a high level of glucose in the bloodstream triggered by inadequate insulin output or insulin activity." (PMID 35685730, 2022). "We explored parents' views about healthcare professionals having remote access to their young child's insulin and glucose data during a clinical trial to inform use of data sharing in routine pediatric diabetes care." (PMID 35561092, 2022). "Another ALMS mouse model, the fat aussie mouse with exon 8 Alms1 deletion, develops spontaneous diabetes with elevated fasting glucose and glucose intolerance, where even massive islet hyperplasia cannot produce enough insulin to match the demand." (PMID 35813631, 2022). "In this research, data of the DehPCS study were used to assess the validity of self-reported diabetes based on the reference criteria, including the history of taking oral anti-diabetic drugs, insulin injection, or high fasting blood sugar." (PMID 35619088, 2022). "INS is believed to play a central role in insulin‐dependent diabetes, permanent neonatal diabetes, type 10 juvenile mature diabetes, and hyperinsulinemia." (PMID 35343091, 2022). "These applications assist in insulin administration, diet plans, awareness programs, and motivation to control diabetes." (PMID 35233335, 2022). "The use of flash glucose monitoring (FGM) in conjunction with proper education has been reported to improve glycemic control in people with diabetes on insulin therapy." (PMID 36506077, 2022). "The results indicate that the marine algae Ulva reticulata is a promising candidate for managing diabetes by inhibiting carbohydrate metabolizing enzymes and promoting insulin secretion." (PMID 36557959, 2022). "Hyperglycemia is a major risk factor for type 2 diabetes mellitus (T2DM), as it causes the improper secretion and activation of insulin." (PMID 36039271, 2022). "In short, the fact that the homeostasis of insulin and other glucocorticoid hormones is disrupted, resulting in the absolute or relative insufficiency of insulin will lead to diabetes." (PMID 36188222, 2022). "The mean age of the participants in the study was 52.82 ± 13.48 years, the mean blood glucose level was 172.74 ± 44.54 mg/dL, the mean duration of diabetes was 14.37 ± 12.22 years, and the mean duration of insulin use was 9.13 ± 12.24 years." (PMID 36945997, 2022). "Type 2 diabetes mellitus was treated in 19.5% in the first group and 22.6% in the second; in both groups, more than 50% of patients were treated with insulin, whereas metformin was the most commonly prescribed anti-diabetic drug." (PMID 33909256, 2022).